ENSG00000285130 (novel protein)
Gene: Protein-coding gene on chromosome 9 (69,035,747 to 69,255,187, forward strand). Ensembl gene ENSG00000285130.
Genetic constraint (gnomAD): Loss-of-function variants: 88 observed, 130.08 expected, observed/expected ratio (o/e) 0.68, 90% interval 0.57 to 0.81. Missense variants: 1,639 observed, 1,688.8 expected, observed/expected ratio (o/e) 0.97, 90% interval 0.93 to 1.01. Synonymous variants: 636 observed, 633.65 expected, observed/expected ratio (o/e) 1, 90% interval 0.94 to 1.07.